SGMS1 (sphingomyelin synthase 1)
Description:
Major sphingomyelin synthase at the Golgi apparatus. Catalyzes the reversible transfer of phosphocholine moiety in sphingomyelin biosynthesis: in the forward reaction transfers phosphocholine head group of phosphatidylcholine (PC) on to ceramide (CER) to form ceramide phosphocholine (sphingomyelin, SM) and diacylglycerol (DAG) as by-product, and in the reverse reaction transfers phosphocholine from SM to DAG to form PC and CER. The direction of the reaction depends on the levels of CER and DAG in Golgi membranes. Converts the newly synthesized CER, that is transported from the endoplasmic reticulum to the trans-Golgi by the Cer transport protein (CERT), to SM. Can form a heteromeric complex with glucosylceramide synthase (GCS) increasing SMS activity and reducing glucosylceramide synthesis, a critical mechanism that controls the metabolic fate of CER in the Golgi. Does not use free phosphorylcholine or CDP-choline as donor. Can also transfer phosphoethanolamine head group of phosphatidylethanolamine (PE) on to CER to form ceramide phosphoethanolamine (CPE) (By similarity). Regulates receptor-mediated signal transduction via mitogenic DAG and proapoptotic CER, as well as via SM, a structural component of membrane rafts that serve as platforms for signal transduction and protein sorting. Plays a role in secretory transport via regulation of DAG pool at the Golgi apparatus and its downstream effects on PRKD1.
Synonyms: MOB; SMS1; TMEM23; MGC17342; MOB1; hmob33
Tractability: Antibody: its Gene Ontology location is reachable by antibodies, with high confidence; UniProt predicts a signal peptide or a membrane-spanning region. PROTAC: ubiquitination databases record sites on it; a small molecule that binds it is known.
Target class: Enzyme; Transferase
Gene: Protein-coding gene on chromosome 10 (50,305,586 to 50,625,187, reverse strand). Ensembl gene ENSG00000198964.
Subcellular location: Golgi apparatus membrane
Subcellular location (Human Protein Atlas): Nucleoplasm; Cytosol; Golgi apparatus; Nucleoli fibrillar center
Pathways (Reactome):
Metabolism: Sphingolipid de novo biosynthesis
Gene Ontology:
Molecular function: ceramide cholinephosphotransferase activity; ceramide phosphoethanolamine synthase activity; sphingomyelin synthase activity; phosphotransferase activity, for other substituted phosphate groups
Biological process: ceramide biosynthetic process; regulation of glucosylceramide biosynthetic process; sphingomyelin biosynthetic process; regulation of intrinsic apoptotic signaling pathway; sphingolipid biosynthetic process
Cellular component: Golgi membrane; Golgi trans cisterna; Golgi trans cisterna membrane; membrane; endoplasmic reticulum; endoplasmic reticulum membrane; nucleus; plasma membrane
Genetic constraint (gnomAD): Loss-of-function variants: 12 observed, 44.27 expected, observed/expected ratio (o/e) 0.27, 90% interval 0.17 to 0.44. The upper end of that interval is the gene's LOEUF score, 0.44, which puts it in group 1 of 6, group 1 being the genes least tolerant of losing a copy. Missense variants: 304 observed, 492.89 expected, observed/expected ratio (o/e) 0.62, 90% interval 0.56 to 0.68. Synonymous variants: 182 observed, 179.42 expected, observed/expected ratio (o/e) 1.01, 90% interval 0.9 to 1.15.
Homologues: Orthologues: macaque SGMS1 (100% identical), chimpanzee SGMS1 (99% identical), mouse Sgms1 (98% identical), pig SGMS1 (98% identical), rabbit SGMS1 (97% identical), rat Sgms1 (97% identical), guinea pig SGMS1 (96% identical), dog SGMS1 (93% identical), tropical clawed frog sgms1 (72% identical), zebrafish sgms1a (67% identical), zebrafish sgms1b (66% identical), Caenorhabditis elegans sms-1 (29% identical). Paralogues in human: SGMS2 (52% identical), SAMD8 (36% identical).
Diseases named in the same sentence as SGMS1 in open-access papers:
SGMS1 is named in the same sentence as 47 diseases in open-access papers, as found by Europe PMC text mining. Sharing a sentence is not in itself a finding about the gene and the disease. The quoted sentences say what the papers report.
melanoma (6 papers, 2019 to 2026). A malignant, usually aggressive tumor composed of atypical, neoplastic melanocytes. "SGMS1 is expressed at low levels in most of the human melanoma biopsies and low SGMS1 expression is associated with a worse prognosis in metastatic melanoma patients." (PMID 32858889, 2020). "Bilal F., Montfort A., Gilhodes J., Garcia V., Riond J., Carpentier S.,Filleron T., Colacios C., Levade T., Daher A., Meyer N., Andrieu Abadie N., Ségui B. Sphingomyelin synthase 1 (SMS1) downregulationis associated with sphingolipid reprogramming and aworse prognosis in melanoma." (PMID 39944803, 2024). "To get insight into the molecular mechanisms that may account for SMS1 downregulation and/or inhibition of enzyme activity, we evaluated SGMS1 mutation and methylation status in the public databases of melanoma." (PMID 31114500, 2019). "It was recently provided evidence that SGMS1, the gene encoding SM synthase 1 (SMS1), is frequently downregulated in melanoma and SMS1 downregulation is associated with a bad prognosis in metastatic melanoma patients." (PMID 33121001, 2020). "Accordingly, melanoma cells exhibited low SGMS1 and SGMS2 expression, while they expressed UGCG at higher levels." (PMID 31114500, 2019). "In addition, CER metabolism in melanoma is significantly affected by the downregulation of sphingomyelin synthase 1 (SMS1), the enzyme responsible for converting CER into SM." (PMID 41596686, 2026). "Strikingly, melanoma exhibited the lowest expression of SGMS1." (PMID 31114500, 2019). "Accordingly, various human melanoma cells displayed a SL metabolism signature associated with (i) a robust and a low expression of UGCG and SGMS1/2, respectively, (ii) higher in situ enzyme activity of GCS than SMS, and (iii) higher intracellular levels of GlcCer than SM." (PMID 31114500, 2019).
metastatic melanoma (5 papers, 2019 to 2024). A melanoma that has spread from its primary site to another anatomic site. "To delineate the effect of DNA methylation on the regulation of SGMS1 expression, we analyzed the TCGA metastatic melanomas." (PMID 31114500, 2019). "Finally, the clinical outcome in metastatic melanoma patients exhibiting low (20th percentile, medium (between the 20th and 80th percentile), high (80th percentile) SGMS1, SGMS2, and UGCG expression was analyzed in the TCGA cohort." (PMID 31114500, 2019). "Moreover, 4 deep deletions were identified as well as 17 CpG located on the two CpG islands and their shores, the methylation of which was correlated with SGMS1 downregulation in metastatic melanoma." (PMID 31114500, 2019). "In metastatic melanoma from the TCGA, the expression of UGCG was significantly higher than that of SGMS1 and SGMS2." (PMID 31114500, 2019). "Thus, hypermethylation of CpG islands and hypomethylation events in open sea were significantly associated with the decrease in SGMS1 expression, indicating the regulation of SMS1 expression in metastatic melanoma might rely, at least partly, on DNA methylation of the SGMS1 locus." (PMID 31114500, 2019).
breast carcinoma (4 papers, 2015 to 2025). "The nearest gene is SGMS1, a sphingomyelin synthase, which, if overexpressed in breast cancer cell lines, inhibits TGF-β1-induced EMT and the migration and invasion of cells." (PMID 40229280, 2025). "To confirm our findings, we also determined the level of Sphingomyelin synthase 1(SGMS1) in breast cancer tissues." (PMID 32170160, 2020). "Sphingolipids were identified in breast cancer patients, and genes related to metabolism, such as CERK, SPHK1, and SGMS1, were verified by a TCGA cohort." (PMID 34549263, 2021).
glioma (4 papers, 2019 to 2024). A benign or malignant brain and spinal cord tumor that arises from glial cells (astrocytes, oligodendrocytes, ependymal cells). "Major progress in the therapy of glioma was achieved with synthetic 2-hydroxyoleic acid (2-OHOA), which proved to be a highly specific activator of the SGMS1 isoform with a significantly higher bioavailability and lower toxicity compared to TMZ when administered in therapeutic doses." (PMID 39723240, 2024).
leukemia (3 papers, 2017 to 2022). A malignant (clonal) hematologic disorder, involving hematopoietic stem cells and characterized by the presence of primitive or atypical myeloid or lymphoid cells in the bone marrow and the blood. "It has been suggested that miR-130b regulates growth arrest in B-lymphoid differentiation, and these mechanisms contribute to the direct downregulation of tumor suppressor genes NR2F6 and SGMS1 in MLL-rearranged leukemia." (PMID 36278683, 2022).
Obesity (3 papers, 2021 to 2023). Accumulation of substantial excess body fat. "Our data also revealed that a duplication in the first intron of the SGMS1 (Small G Protein Signaling Modulator 1) gene may lead to reduced body weight and a lower risk of obesity." (PMID 37799139, 2023). "Sgms1 and Degs2, which encode proteins required for the production of sphingolipids, showed highly enriched expression in brain ECs and were upregulated in obesity, particularly in the art cluster." (PMID 36400935, 2022). "SGMS1 is localised in the Golgi apparatus and has previously been related to cell growth, whereas SGMS2 is mainly found at the plasma membrane and has been linked to obesity and insulin resistance." (PMID 33770195, 2021). "Notably, SGMS1-null mice present with insulin secretion deficiencies and mitochondrial dysfunction, whereas SGMS2 knockout mice are protected against high-fat diet-induced obesity and insulin resistance." (PMID 33770195, 2021).
diabetes (2 papers, 2022 to 2023). "SGMS1, SGPL1, and SPTSSB showed increased expression only in transplanted islets with recurrent diabetes (Tx)." (PMID 36589856, 2022).
Hearing impairment (2 papers, 2013 to 2024). A decreased magnitude of the sensory perception of sound. "Sgms1 encodes sphingomyelin synthase 1, an enzyme in the sphingosine-1-phosphate signalling pathway, and was previously reported to underlie hearing impairment in the mouse." (PMID 39067415, 2024).
Hepatitis (2 papers, 2022 to 2023). Inflammation of the liver. "Moreover, Sgms1-/- mice were reported to show diminished sensitivity to Con-A-induced hepatitis." (PMID 36494334, 2022).
lipodystrophy (2 papers, 2013 to 2018). A congenital or acquired disorder characterized by abnormal loss or redistribution of the adipose tissue in the body. "Sphingomyelin synthase 1 (Sms1) KO mice have been shown to have a severe lipodystrophy, with evidence of adipocyte cell death." (PMID 29415989, 2018).
colitis (1 paper, 2023). Inflammation of the colon. "SGMS1 was a predicted target of baicalin in a study of the baicalin sphingolipid-linked treatment of colitis." (PMID 37808875, 2023).
COVID-19 (1 paper, 2023). A disease caused by infection with severe acute respiratory syndrome coronavirus 2. "Conversely, the expression levels of enzymes involved in the conversion of Cer to SM, such as sphingomyelin synthase 1 (SGMS1), were significantly increased in COVID-19 patients in a severity-dependent manner." (PMID 37566018, 2023).
malnutrition (1 paper, 2025). Inadequate nutrition resulting from poor diet, malabsorption, or abnormal nutrient distribution. "Interestingly, SGMS1 deficiency has been linked to adipose tissue atrophy, reduced lipoprotein lipase activity, elevated plasma triglyceride levels, impaired fatty acid uptake, and malnutrition." (PMID 40005876, 2025).
monocytic leukemia (1 paper, 2018). "SGMS1-AS1, a lncRNA located on the antisense strand of sphingomyelin synthase 1 (SGMS1), may play a role in D609-induced apoptosis in U937 human monocytic leukemia cells." (PMID 29416790, 2018).
osteoporosis (1 paper, 2025). A condition of reduced bone mass, with decreased cortical thickness and a decrease in the number and size of the trabeculae of cancellous bone (but normal chemical composition), resulting in increased fracture incidence. "Previous genetic studies have identified variants in the sphingomyelin synthase gene (SGMS1) that are linked to osteoporosis." (PMID 40560432, 2025). "Furthermore, presence of specific gene mutation in SGMS1 has been linked to early onset osteoporosis and cranial sclerosis, providing a genetic backdrop to our findings." (PMID 40560432, 2025).
ZIKV infection (1 paper, 2020). "To test this experimentally, we infected a KBM7 cell line containing an inactivating mutation for SGMS1, the enzyme responsible for most SM synthesis in mammalian cells, and observed significant enhancement of ZIKV infection in SGMS1GT cells." (PMID 32694525, 2020). "Indeed, KBM7 SGMS1GT cells were over 100-fold more permissive to ZIKV infection than WT or SGMS1GT + SGMS1 cells, suggesting that even modest increases in pools of intracellular ceramide could dramatically enhance viral replication." (PMID 32694525, 2020).
cancer (11 papers, 2010 to 2024). A tumor composed of atypical neoplastic, often pleomorphic cells that invade other tissues. "FASN (fatty acid protein synthase) together with SGMS1 (sphingomyelin synthase 1) are involved in several types of cancer and are regulated by the ABL proto-oncogene." (PMID 36291756, 2022). "We next evaluated the expression of SGMS1 in various cancer types from the TCGA database." (PMID 31114500, 2019). "In addition, mRNAs for two of the three enzymes that also utilize Cer for biosynthesis of other sphingolipids (sphingomyelin synthase 1, SMS1, and ceramide kinase, CERK) and the Cer transport protein CERT appear to be lower for the carcinoma cells versus normal stromal tissue." (PMID 20624317, 2010).
tumor (11 papers, 2016 to 2023). "In the local cohort, we did not observe any significant difference in the mRNA expression of SGMS1 between tumor and adjacent normal tissues, though it was found to be significantly downregulated in TCGA cohort." (PMID 32170160, 2020). "In contrast, TCGA cohort exhibited significant downregulation of SGMS1 in tumor tissues as compared to adjacent normal tissues." (PMID 32170160, 2020). "The tumor-associated significance of the other seven genes (HIST2H2AA4, UQCRHL, AC008269.1, RAB6D, APOL4, HIST1H2AI, ANKAR, SGMS1) remains unclear." (PMID 35480120, 2022).
infection (8 papers, 2011 to 2025). The state of being infected such as from the introduction of a foreign agent such as serum, vaccine, antigenic substance or organism. "Sphingomyelin synthase 1 deficiency was also found to reduce JEV load in the cells after infection, suggesting an association between sphingomyelin synthase 1 present on the cell membrane and JEV attachment and infection." (PMID 38139132, 2023). "Furthermore, among the panel of gene-edited HeLa/mCAT#8 cells, no infection of VSVFLuc/RuV-CE2E1 was observed in SGMS1-knockout cells." (PMID 36346228, 2022).
SGMS1 also shares sentences with these, for which no sentence is quoted: atherosclerosis (4 papers); liver fibrosis (2); nonalcoholic steatohepatitis (2); breast tumor (1); cervical carcinoma (1); chlamydial infection (1); dengue (1); depression (1); encephalitis (1); fatty liver (1); head and neck cancer (1); hepatoma (1); hyperlipidemia (1); infertile (1); Insulin resistance (1); intestinal cancer (1); intestinal diseases (1); liver disease (1); lymphoma (1); male infertility (1); meningitis (1); metabolic disease (1); nevus (1); nonalcoholic fatty liver diseases (1); ovarian carcinoma (1); pancreatic cancer (1); steatosis (1); Thrombocytopenia (1).